SIRT1 (sirtuin 1)
Diseases named in the same sentence as SIRT1 in open-access papers (continued):
Sharing a sentence is not in itself a finding about the gene and the disease.
tumor (continued). "This indicated that the chances of metastasis were enhanced when SIRT1 is overexpressed which in turn influences the exosomes concentration in the tumor cells." (PMID 35496046, 2022). "The other members of the sirtuin family, SIRT2–7, similar to SIRT1, can also act as oncogenes or tumour suppressors according to the type of tumour." (PMID 36078035, 2022). "Five studies including 656 cases reported relationship between SIRT1 expression and tumor size in ESCC." (PMID 35350833, 2022). "The cases with positive SIRT1 expression were 269 among 452 cases in the tumor stage (III + IV) of ESCC, with a positive rate of 59.51%." (PMID 35350833, 2022). "In tumor, some researchers have shown the opposite effects of SIRT1 as an oncoprotein or a tumor suppressor under different conditions." (PMID 35212616, 2022). "The cases with positive SIRT1 expression were 176 among 359 cases in the tumor stage (I + II) of ESCC, with a positive rate of 49.03%." (PMID 35350833, 2022). "Its beneficial effects have been attributed to its anti-inflammatory, antioxidant, anti-aging (due to increase in SIRT1), and anti-tumor properties." (PMID 36361735, 2022). "They found that NAMPT inhibited the tumorigenesis of neutrophils by inhibiting SIRT-1 signal transduction and then blocked the transcription of angiogenic genes to play an anti-tumor role." (PMID 35906622, 2022). "SIRT1 increases MYC transcriptional activity through deacetylation, which in turn increases NAD+ through increased expression of NAMPT, thereby enhancing SIRT1 activity, and this positive feedback inhibits tumor cell senescence and apoptosis." (PMID 36523971, 2022). "Increased expression of SIRT1, FoxO1 and FoxO3a in the 67NR group confirms our results which related to the metastatic character of the tumor." (PMID 36142156, 2022). "Previous studies have shown that SIRT1 is downregulated in GC and inhibits GC cell proliferation and xenografted tumor growth." (PMID 36499440, 2022). "SIRT-1 activator metformin can also limit harmful Th17 amplification by reducing IL-17 A and exerting an anti-tumor effect." (PMID 35906622, 2022). "SIRT1 reduction promotes EMT, metastasis, and tumor progression in breast and kidney epithelial cells associated with TGFβ hyperactivation and Smad4 hyperacetylation." (PMID 35745656, 2022). "For example, PPARD agonist has been shown to increase SIRT1 protein levels, which is a tumor promoter in LA." (PMID 35342393, 2022). "So far, studies have shown SIRT1 can have both a tumor-suppressor and a tumor-promoter effect depending on its predominant localization—cytoplasmatic versus nuclear—or on the cell type on which is overexpressed, normal hepatocytes versus HCC cells." (PMID 36291868, 2022). "The effect of melatonin on the expression of SIRT1 also revealed downregulation or upregulation, in which case a marked difference was observed between tumor and non-tumor cells." (PMID 35795579, 2022). "For instance, high expression of SIRT1 and SIRT7 is highly associated with poor survival, whereas low tumor levels of SIRT4 predicts a decreased survival time in HCC patients." (PMID 36581622, 2022).
tumor (continued). "SIRT1 expression depends on tumor type, microenvironmental complexity and the effects of cellular stress, such as caloric restriction, starvation conditions (fasting) or the presence of ROS." (PMID 36499440, 2022). "The cases with positive SIRT1 expression were 130 among 301 cases in tumor infiltration (T1 + T2) of ESCC, with a positive rate of 43.19%." (PMID 35350833, 2022). "SIRT1 activation can prevent tumor vascularization through Notch pathway inhibition and can suppress tumor cell survival by inducing apoptosis in cancer cells through FOXO activation." (PMID 36361882, 2022). "It has been repeatedly shown that in non-tumour cells, SIRT1 expression is stimulated by melatonin, and the effects of melatonin are suppressed by SIRT1 inhibitors." (PMID 35456927, 2022). "In vitro study showed that FGF21 was elevated in tumor cells compared with normal lung cell lines, which facilitated tumor progression by promoting cell growth, migration, and defending oxidative stress via Sirtuin 1/PI3K/AKT signaling." (PMID 36263162, 2022). "It was observed that SIRT1 stimulates autophagy in tumor stroma under oxidative stress conditions, which aids endothelial cell survival." (PMID 35912261, 2022). "It is worth noting that both AKT2 and SIRT1 are related to tumor prognosis and drug resistance, and also gene targets of miR-124-3p.1." (PMID 35013144, 2022). "We first confirmed the SIRT-1 inducing effect of adiponectin in tumor tissues by western blot analysis and IHC." (PMID 34986886, 2022). "SIRT1 is implicated in EMT activation, and its function in DNA repair and cell cycle control was found to be similar to that of a tumor promoter gene." (PMID 35853978, 2022). "GAP43 can inhibit the formation of microtubules in tumor and intertumor cell network connections and induce apoptosis through the SIRT1 signaling pathway." (PMID 35884600, 2022). "In this situation, miR-204 acts as a tumor suppressor, while SIRT1 downregulation induces a MET phenotype, with a decrease in Vimentin and an increase in E-cadherin expression." (PMID 35745656, 2022). "More precisely, SIRT1 expression has been shown to be correlated with sex, age, histological type, grade, tumor size, tumor invasion, elevated serum levels of carcinoembryonic antigens, LNM, and TNM stage." (PMID 36358890, 2022). "Together, we identified SYT8 to be a central regulator of tumor progression involving signaling via the SIRT1, ERRα, and TNNI2 axis." (PMID 34907162, 2021). "Human SIRT1 is related to tumor proliferation, metastasis, and invasion in esophageal cancer, CRC, and breast cancer." (PMID 34660182, 2021). "Consistent with accelerated tumor growth, the proportion of Ki67-positive cells was significantly higher in the SIRT1-overexpressing group compared with the control vector group." (PMID 34163012, 2021).
tumor (continued). "Contrarily, it has also been shown that SIRT1 overexpression can magnify tumor enlargement and support cell endurance in response to drug resistance and stress." (PMID 33705642, 2021). "SIRT1 upregulation triggers mitobiogenesis via PGC1α and correlates with tumor microvascular invasion, advanced TNM score and predicted HCC recurrence." (PMID 33920670, 2021). "Recent studies have shown that silent information regulator 2 homolog 1 (SIRT1), a class 3 histone deacetylase, is involved in regulating the invasion and metastasis of various tumor cells." (PMID 34934771, 2021). "SIRT1 overexpression increases the expression of c-Myc, a key oncoprotein that increases the expression of many tumor proliferating genes." (PMID 34650436, 2021). "Sirt1 functions in tumour have been widely discussed, indicating an effect as both a tumour suppressor and oncogenic factor, depending on the cell context." (PMID 33650791, 2021). "Patients with higher Sirt1 expression in tumor tissues exhibited significantly shorter overall survival." (PMID 33854041, 2021). "Based on our analysis, we suggest that SIRT1 has a tumor suppressing role in mTOR-driven HCC tumors." (PMID 34348664, 2021). "Our own studies identified increased protein expression of the metabolic sensor SIRT1 in the tumor cells of metastatic EwS." (PMID 33919988, 2021). "MiR-34a is considered a tumor suppressor gene that it is known to regulate SIRT1 expression (silent information regulator 1)." (PMID 34771655, 2021). "The role of SIRT1 in tumorigenesis is debated due to conflicting reports on SIRT1 as a tumor promoter or suppressor." (PMID 34348664, 2021). "PGC-1α is a key regulatory target of sirtuin-1 (SIRT1), which can act as a tumor promoter or suppressor depending on the tumor cell type." (PMID 34440674, 2021). "Dunnione restored reduced SIRT1 activity in lung tissues of tumor-bearing mice by augmentation of NAD+, thus deacetylating NF-κB and reducing NF-κB activity, resulting in decreased TF expression and activity." (PMID 34769515, 2021). "In orthopedic tumor xenograft mice model with HepG2 hepatocarcinoma cells, Cambinol significantly reduced tumor growth, which was consistent with the SIRT1 knockdown results of in vivo intrahepatic xenograft mouse model." (PMID 34650436, 2021). "SIRT1 interacts and deacetylases c-Myc, decreasing its stability, which suggests that SIRT1 plays a role in tumor suppression." (PMID 34769241, 2021). "Another study explained that SIRT1 supports tumor development by making the tumor “addicted” to sirtuins." (PMID 34638362, 2021). "Overexpression of SIRT1 stimulated RBE-shUSP22 tumour xenograft growth—the sizes and the weights of the RBE-shUSP22 + SIRT1 tumours were twofold greater than the RBE-shUSP22 control (p < 0.05)." (PMID 34226501, 2021). "Compared to the control, we identified a total of 2506 upregulated genes and 2229 downregulated genes (fold change > 1.2, p < 0.001) in SIRT1-overexpressing tumor samples." (PMID 34163012, 2021). "In EGFR-TKI-resistant xenograft models, the combined administration of a SIRT1 inhibitor, tenovin-6 (Tv6), with gefitinib promoted tumor regression." (PMID 34381712, 2021). "Because SIRT1 affects tumor metastasis and malignancy, SIRT1 is considered to be a key regulator of EMT." (PMID 34934771, 2021). "By knockdown/rescue experiments, fluorometric Sirt1 activity assay, immunoprecipitation, and pull-down assays, we identify here that the tumor suppressor LKB1 (liver kinase B1) as a direct activator of Sirt1 elicited by resveratrol." (PMID 34216621, 2021). "Accordingly, tyrosinase-reactive hybrid Th1/17 cells differentiated ex vivo in the presence of Ex527 (Sirt1 inhibitor) displayed a lower anti-tumor activity than untreated cells in a murine melanoma model." (PMID 33936090, 2021). "We found that NAD+ level and SIRT1 were significantly decreased in the lungs of tumor-bearing mice compared with normal mice." (PMID 34769515, 2021).
tumor (continued). "We found that NAD+ and SIRT1 expression was significantly reduced in the lung tissues of 4T1 tumor-bearing mice compared with that in normal mice, but was restored by dunnione." (PMID 34769515, 2021). "SIRT1 also behaves as a tumor suppressor based upon its character in down-regulating survivin and β-catenin." (PMID 33705642, 2021). "Activation of SIRT1 was thought to be protective against age-related diseases, including the ability to improve glucose tolerance, inhibit tumor progression, and regulate the metabolism of lipid and cholesterol." (PMID 34804363, 2021). "A particular region on PLD2 is required to activate SIRT1, this activation leading to protection of tumor cells from apoptosis induced by the chemotherapy drug etoposide." (PMID 34471223, 2021). "The aberrant expression of SIRT1 regulated tumor cell metastatic capacity through the promotion of epithelial-mesenchymal transition (EMT)." (PMID 33804155, 2021). "Apparently, dual functions of SIRT1 play either protumourigenesis or antitumourignesis, depending on the cellular context of tumour types." (PMID 34226501, 2021). "The NOD/SCID mouse xenograft models showed that SIRT1 not only significantly promoted tumor growth, but also tumor-initiating capacity and CSC frequency, thus clarifying its role in promoting pancreatic CSCs." (PMID 34163012, 2021). "In T cells, Sirt1 enhances the activity of Foxo1 by deacetylating Foxo1, and promotes the expression of Klf2 and Ccr7 genes, thereby improving the anti-tumor immune response of T cells." (PMID 34880761, 2021). "When AAV-NT mice were treated with 6-chloro-2,3,4,9-tetrahydro-1H-carbazole-1-carboxamide (EX-527), a selective and potent inhibitor of SIRT1, the anti-inflammatory and anti-tumor properties of SIRT1 were reversed." (PMID 33922238, 2021). "In vivo experiments implied that SIRT1 promoted established tumor xenograft growth, increased tumor-initiating capacity in NOD/SCID mice, and increased CSC frequency." (PMID 34163012, 2021). "SIRT1 is involved in the regulation of cell divisions, aging, and metabolism and can function as both a tumor suppressor and an oncoprotein." (PMID 34698105, 2021). "Lastly, pharmacological inhibition of NAD+ and Sirt1 leads to direct inhibition of Klf2 and Ccr7, thus confirming that the NAD+-Sirt1 axis regulates differentiation, migration, effector functions and the anti-tumor response of Th1/17 cells." (PMID 33936090, 2021). "Analysis of the postoperative pathology of clinical patients indicated that, compared with patients with low circ-SIRT1 expression, those with high expression of circ-SIRT1 had greater depth of tumor invasion." (PMID 34660182, 2021). "Previous studies suggest that the NAD-dependent deacetylase sirtuin 1 (SIRT1) has a dual role in hematologic malignancies, acting as a tumor suppressor or tumor promoter depending on the tumor type." (PMID 34407842, 2021). "The downregulation of SIRT1 significantly reduced the viability of tumor cells overexpressing FBXW11." (PMID 34642302, 2021). "In tumor microenvironments, Sirt1 participates in the immune response by activating the pro-inflammatory pathway." (PMID 34880761, 2021). "We extended that further by showing that USP22 deubiquitination was associated with SIRT1 stabilisation, subsequently transducing Akt and ERK tumour survival signal." (PMID 34226501, 2021). "In contrast, SIRT1 causes silencing of Survivin via deacetylation of H3K9, which inhibits BC-related gene transcription, expression, and ultimately tumor growth." (PMID 34595180, 2021). "Administration of Res stimulates the activation of Sirt1 leading to the cell cycle arrest and induction of senescence in tumor cell of nude mice." (PMID 33478512, 2021).
tumor (continued). "Once up-regulated, Sirt1 can promote tumor progression by deacetylating multiple proteins in HCC cells." (PMID 33854041, 2021). "SIRT1 (silent information regulator is a protein deacetylase that is related to the proliferation and apoptosis of tumor cells." (PMID 33953786, 2021). "Depending on the expression status and cellular context, SIRT1 acts as a tumor suppressor or as an oncogene and resistance mechanism to doxorubicin." (PMID 34638362, 2021). "To identify the mechanism behind SYT8-mediated regulation of tumor metastasis, we investigated the role of SIRT1, a protein deacetylase that plays a wide role in regulating the cell cycle during apoptosis." (PMID 34907162, 2021). "Inhibition of either PARP1 or SIRT1 alone or in combination with chemotherapy has an advantage in eliminating tumors or inhibiting tumor invasion." (PMID 34445574, 2021). "Sirt1 is an important assessment marker for tumor cell remodeling and the mitochondrial metabolic shift to OXPHOS and resistance to cisplatin treatment." (PMID 34868997, 2021). "Most of the evidence shows that SIRT1 can act as a tumor promoter; however, there is some evidence that suggests it is a tumor suppressor." (PMID 33384409, 2021). "Conversely, SIRT1 also deacetylates and represses the oncogenic transcription factor β-catenin, suggesting a role as a tumor suppressor." (PMID 34348664, 2021). "We further extracted total protein and RNA from tumor samples and verified SIRT1 overexpression by western blotting." (PMID 34163012, 2021). "Sirt1 genetic ablation (Sirt1−/−) mitigated tumor growth and invasiveness in both in vitro and in vivo models." (PMID 33920670, 2021). "SIRT1, a direct downstream target of HIF-1α, is a critical regulator of endothelial cell behavior and has been linked to tumor angiogenesis under hypoxic conditions." (PMID 34381712, 2021). "SIRT1, as an important transcriptional target of HIC1, is transcriptionally upregulated in tumor cells due to the loss of HIC1." (PMID 34642302, 2021). "SIRT1 knockdown inhibited USP22-induced HCCC tumour growth, and the sizes and weights of these tumours were almost half of the HCCC-USP22 (p < 0.05)." (PMID 34226501, 2021). "A recent study exhibits that inhibition of SIRT1 by caveolin-1 in senescent fibroblasts promotes the secretion of interleukin 6 (IL-6) and stimulates tumor growth." (PMID 33390835, 2021). "SIRT1 is a key anti-apoptotic factor in tumor cells, and SIRT1 activity was found to be activated by chemotherapeutic agents in certain tumor cell lines." (PMID 34381712, 2021). "Pyroptosis triggered in SIRT1‐knockdown cells can be transmitted to naïve tumor cells via the intercellular transmission of the AIM2 inflammasome, whereas pyroptotic death signaling can be prevented by SIRT1 restoration." (PMID 34014039, 2021). "A great deal of research has shown that SIRT1 promotes cell survival by inhibiting apoptosis, and thus, for several decades it has been recognized as a tumor promoter." (PMID 33917352, 2021). "Meanwhile, co-treatment of Rp1 and ActD also decreased AKT activation to downregulate the expression of SIRT1, and ultimately activated cells apoptosis as well as reversed chemoresistance in tumor cells." (PMID 34975466, 2021). "Our present study defines USP22 as a poor prognostic predictor in iCCA that cooperates with SIRT1 and facilitates tumour development." (PMID 34226501, 2021). "In recent years, an increasing number of studies have shown that SIRT1 not only plays a regulatory role in the inflammatory response but also has a close relationship with oxidative stress, glial cell proliferation and tumor recurrence." (PMID 34395427, 2021). "The enhanced anti-tumor cells were dependent on the increased NAD(+)-dependent activity of the histone deacetylase Sirt1." (PMID 34026764, 2021).